GLUD1 (glutamate dehydrogenase 1)
Description:
Mitochondrial glutamate dehydrogenase that catalyzes the conversion of L-glutamate into alpha-ketoglutarate. Plays a key role in glutamine anaplerosis by producing alpha-ketoglutarate, an important intermediate in the tricarboxylic acid cycle. Plays a role in insulin homeostasis. May be involved in learning and memory reactions by increasing the turnover of the excitatory neurotransmitter glutamate (By similarity).
Synonyms: GLUD; GDH; GDH1; hGDH1
Tractability: Small molecule: it has a binding pocket of medium quality. PROTAC: ubiquitination databases record sites on it; its protein half-life has been measured.
Gene: Protein-coding gene on chromosome 10 (87,050,202 to 87,095,049, reverse strand). Ensembl gene ENSG00000148672.
Subcellular location: Mitochondrion; Endoplasmic reticulum
Subcellular location (Human Protein Atlas): Mitochondria
Pathways (Reactome):
Metabolism: Glutamate and glutamine metabolism
Metabolism of proteins: Mitochondrial protein degradation
Organelle biogenesis and maintenance: Transcriptional activation of mitochondrial biogenesis
Gene Ontology:
Molecular function: ADP binding; glutamate dehydrogenase (NAD+) activity; glutamate dehydrogenase (NADP+) activity; glutamate dehydrogenase [NAD(P)+] activity; GTP binding; L-leucine binding; NAD+ binding; protein binding; protein homodimerization activity; oxidoreductase activity; oxidoreductase activity, acting on the CH-NH2 group of donors, NAD or NADP as acceptor
Biological process: L-glutamate biosynthetic process; L-glutamate catabolic process; positive regulation of insulin secretion; substantia nigra development; glutamine metabolic process; tricarboxylic acid metabolic process; amino acid metabolic process
Cellular component: cytoplasm; endoplasmic reticulum; mitochondrion; mitochondrial matrix
Genetic constraint (gnomAD): Loss-of-function variants: 16 observed, 32.49 expected, observed/expected ratio (o/e) 0.49, 90% interval 0.33 to 0.75. The upper end of that interval is the gene's LOEUF score, 0.75, which puts it in group 3 of 6, group 1 being the genes least tolerant of losing a copy. Missense variants: 322 observed, 504.6 expected, observed/expected ratio (o/e) 0.64, 90% interval 0.58 to 0.7. Synonymous variants: 168 observed, 194.86 expected, observed/expected ratio (o/e) 0.86, 90% interval 0.76 to 0.98.
Gene-disease validity (ClinGen):
ClinGen rates the evidence that GLUD1 causes each of these diseases.
hyperinsulinism-hyperammonemia syndrome (autosomal dominant): Definitive.
Homologues: Orthologues: chimpanzee GLUD1 (99% identical), macaque GLUD1 (99% identical), mouse Glud1 (98% identical), rat Glud1 (97% identical), dog GLUD1 (96% identical), pig GLUD1 (94% identical), tropical clawed frog glud1 (87% identical), zebrafish glud1a (83% identical), Drosophila melanogaster Gdh (67% identical), Caenorhabditis elegans gdh-1 (58% identical), Drosophila melanogaster bb8 (44% identical). Paralogues in human: GLUD2 (96% identical).
Diseases named in the same sentence as GLUD1 in open-access papers:
GLUD1 is named in the same sentence as 98 diseases in open-access papers, as found by Europe PMC text mining. Sharing a sentence is not in itself a finding about the gene and the disease. The quoted sentences say what the papers report.
hyperinsulinism (23 papers, 2008 to 2025). Abnormally high levels of insulin in the blood. "GLUD1: Heterozygous GLUD1 gain-of-function variants are associated with hyperinsulinism-hyperammonemia syndrome." (PMID 38963811, 2025). "Human genetic variants in GLUD1 cause hyperinsulinism–hyperammonemia syndrome, which features neurological symptoms such as seizure and intellectual disability 36,37." (PMID 40766417, 2025). "Congenital hyperinsulinemia (CHI) is a leading cause of recurrent hypoglycemia in infants, often stemming from genetic mutations such as in the GLUD1 gene, manifesting as hyperinsulinism-hyperammonemia syndrome (HI/HA)." (PMID 39759686, 2024). "The significance of the co-stimulation of BCAT and GDH reactions can be seen in hyperinsulinism hyperammonemia syndrome, which is caused by activating mutations in GLUD1 that encode GDH isozyme." (PMID 39795113, 2024). "Hyperinsulinism/hyperammonemia syndrome (HI/HA) is an autosomal dominant disorder caused by monoallelic activating mutations in the glutamate dehydrogenase 1 (GLUD1) gene." (PMID 35326344, 2022). "Seventeen patients (35 %) were treated with a leucine-restricted diet, of which all except two patients suffered from the Hyperinsulinism-Hyperammonemia Syndrome (HI/HA) caused by a mutation of the GLUD1 gene." (PMID 26608306, 2015). "Dominant mutations in GLUD1 that cause a loss of allosteric inhibition lead to unusual hyperinsulinism/hyperammonemia syndrome." (PMID 24498361, 2014). "Activating mutations in GLUD1 can lead to hyperinsulinism-hyperammonemia syndrome (OMIM 606762)." (PMID 40973927, 2025). "Mutations in the GLUD1 gene are known to cause hyperinsulinism/hyperammonemia syndrome (HI/HA)." (PMID 38673928, 2024). "For example, an activating mutation in Glud1 causes congenital hyperinsulinism." (PMID 35835371, 2022). "With an incidence of 1 in 200,000, hyperinsulinism-hyperammonemia syndrome ranks as the second most prevalent cause of hyperinsulinism in infancy, attributed to an activating heterozygous mutation in the GLUD1 gene, encoding the intra-mitochondrial enzyme glutamate dehydrogenase (GDH)." (PMID 39759686, 2024). "Gain-of-function mutations in the GLUD1 gene, which encodes the GDH protein, are associated with Hyperinsulinism-Hyperammonemia Syndrome (HHS), a disorder that follows an autosomal dominant inheritance pattern." (PMID 40710547, 2025). "More attention should be paid to the genetic variants of GLUD1 and GLUD2 in patients with hyperinsulinism, inherited predisposition to diabetes, as well as Parkinson’s and Alzheimer’s diseases." (PMID 38673928, 2024). "Gain-of-function mutations in the GLUD1 gene, encoding for glutamate dehydrogenase (GDH), result in the hyperinsulinism/hyperammonemia HI/HA syndrome." (PMID 32143698, 2020). "Among the reported Turkish patients, there was no case with exercise-induced hyperinsulinism (SLC16A1), glucokinase-induced hyperinsulinism, or mutations in the UCP2, HNF4A, and HNF1A genes, while one patient had GLUD1 gene mutation." (PMID 27181376, 2016). "Mutations in eight different genes (ABCC8, KCNJ11, GLUD1, CGK, HADH, SLC16A1, HNF4A and UCP2) have been identified to date in patients with congenital forms of hyperinsulinism (CHI)." (PMID 23032149, 2012). "Two infants had hyperinsulinism-hyperammonemia syndrome due to a GLUD1 mutation but did not suffer any brain injury." (PMID 33424766, 2020). "The presence of persistent hyperammonemia, in most but not all patients with GLUD1 variants, has led to this subtype of hyperinsulinism being referred to as Hyperinsulinism/Hyperammonemia (HI/HA) syndrome (OMIM #606762)." (PMID 32185602, 2020). "In the majority of cases GLUD1 variants arise de novo, with no family history of hyperinsulinism." (PMID 32185602, 2020). "Similar intrafamiliar variability was also reported in dominant forms of hyperinsulinism related to other genes such as SUR1, GCK and GLUD1." (PMID 19065272, 2008).
hyperinsulinism (continued). "The serum ammonia was normal so we ruled out the hyperinsulinism-hyperammonaemia syndrome, the second common form of CHI (caused by mutation in the GLUD1 gene)." (PMID 26064751, 2015).
glioma (22 papers, 2014 to 2024). A benign or malignant brain and spinal cord tumor that arises from glial cells (astrocytes, oligodendrocytes, ependymal cells). "According to that model, the shortage of α-KG in IDHmut gliomas is partially rescued by direct import of glutamate that is converted to α-KG by the NAD+-/NADP+-dependent enzymes glutamate dehydrogenase 1/2 (GLUD1/2)." (PMID 31139406, 2019). "In IDH1MUT glioma, we observed strikingly higher expression levels of GLUD1/2 than in IDH1WT glioma, whereas BCAT1/2 expression levels were much lower in IDH1MUT gliomas than in IDH1WT glioma, as has been reported previously." (PMID 28467784, 2017). "Moreover, immunoblotting results also indicated that the IDH1 mutation increased GLUD1 expression in OGDH-silenced U87 cells, which was consistent with the changes observed in IDH-mutated gliomas." (PMID 39872214, 2024). "Indeed gene expression profiling revealed that GLUD1 and GLUD2 that generate α-ketoglutarate via glutamate oxidation, are selectively and consistently up-regulated in glioma cells harboring IDH mutations." (PMID 28208702, 2017). "The two enzymes converting glutamate to ɑ-KG, GLUD1, and GLUD2, are overexpressed in IDH1-mut tumors, and orthotopic growth of an IDH1-mut glioma line was inhibited by knockdown of GLUD1/2." (PMID 35267433, 2022). "Due to the profound impact on survival in glioma patients, 4 genes, namely IFNGR2, GLUD1, PPIA, and CASP8 were identified." (PMID 36466844, 2022). "Glutamate dehydrogenase 1 (GLUD1) and GLUD2, which catalyze oxidative deamination of glutamate to 2-OG, are significantly elevated in mutIDH1R132H glioma compared with WT IDH1 glioma, indicating the potential for increased glutamate utilization by the TCA cycle." (PMID 35028610, 2021). "Taken together, these results revealed that GLUD2 promotes the growth of IDH1R132H glioma cells in a manner that is not duplicated by overexpression of GLUD1." (PMID 32013066, 2020). "Expression of human GLUD1 did not promote the growth of IDH1R132H murine glioma progenitors, but GLUD2 rescued the growth of these cultures." (PMID 32013066, 2020). "Our analysis suggests an increased contribution of glutamate, rather than glutamine, to the TCA cycle in IDH1MUT glioma, by maintaining high expression levels of GLUD1/2 and silencing or downregulation of BCAT expression." (PMID 28467784, 2017). "In IDHmut non-gliomas, residing in environments with low glutamate concentrations, this rescue pathway may start with the import of glutamine that is first converted to glutamate by mitochondrial glutaminase (GLS), followed by GLUD1/2-mediated further processing to α-KG." (PMID 31139406, 2019). "Conversely, expression of GLUD2 (but not GLUD1) promotes tumor expansion, suggesting that R132H IDH1 glioma cells proliferate by utilizing enhanced glutamate flux through the GLUD2 pathway." (PMID 28208702, 2017).
lung carcinoma (20 papers, 2016 to 2026). "Anoikis resistance was reported in LKB1-deficient lung cancer with an elevated glutamate dehydrogenase 1 (GDH1) that is associated with an increased α-KG, leading to CamKK2-mediated AMPK activation and the repression of mTOR activity." (PMID 33854965, 2021). "In LKB1-deficient lung cancer, glutamate dehydrogenase 1 (GDH1) is upregulated by pleomorphic adenoma gene 1 (PLAG1)." (PMID 32516941, 2020). "Molecular mechanisms indicate that OSC down-regulates the expression of GLUD1, affects the glutamine/glutamate/–KG metabolic axis and mitochondrial oxidative phosphorylation, and inhibits the proliferation and tumor growth of lung cancer cells." (PMID 40507156, 2025). "Previous studies indicated that GLUD1 is involved in the development of glioblastoma, lung cancer, breast cancer, and kidney cancer and affects cellular growth, invasion, and glutamine metabolism." (PMID 38587834, 2024). "With a focus on lung cancer, the increased level of glutamate dehydrogenase 1 (GDH1) shows a significant link to anoikis resistance and metastasis initiation in serine-threonine kinase (LKB1)-deficient NSCLC cells." (PMID 37542350, 2023). "The glutamate-lysing enzyme glutamate dehydrogenase 1 (GDH1) confers anoikis resistance to lung cancer cells by enhancing the binding of substrates to AMPK, which makes lung cancer prone to metastasis." (PMID 37543428, 2023). "GLUD1 was reported to be highly expressed and play the tumor-promoting roles in breast cancer, gastric cancer and lung cancer." (PMID 36203437, 2022). "Since GLUD1 regulated glutaminolysis, ATP production, biosynthesis and affected the occurrence and progression of breast cancer, gastric cancer and lung cancer, and highly proliferative human tumors display high transaminase and low GLUD expression." (PMID 36203437, 2022). "In LKB1-deficient lung cancer, pleomorphic adenoma gene 1 (PLAG1) mediates the upregulation of a glutaminolysis enzyme, glutamate dehydrogenase 1 (GDH1), and calcium/calmodulin-dependent protein kinase kinase 2 bound to AMP-activated protein kinase (AMPK)." (PMID 36230714, 2022). "GLUD1 not only converts glutamate to α-KG but also regulates multiple signaling pathways and downstream genes to modulate the development of kidney cancer, glioblastoma, and lung cancer." (PMID 38587834, 2024). "We found that upregulation of let-7 suppressed the expression of PLAG1, while PLAG1 could promote apoptosis resistance and metastasis of lung cancer by regulating glutamate dehydrogenase 1 (GDH1)." (PMID 36249072, 2022). "GLUD1 regulated redox homeostasis to promote lung cancer cell proliferation." (PMID 36203437, 2022). "Another upregulated and thus potential targetable isoenzyme in lung cancer is GLUD1." (PMID 30634602, 2019). "Moreover, a glutaminolysis enzyme, Glutamate Dehydrogenase 1 (GDH1), upregulated with detachment by pleomorphic adenoma Gene 1 (PLAG1), could provide antianoikis and prometastatic signaling in LKB1‐deficient lung cancer." (PMID 41488744, 2026).
Hyperammonemia (13 papers, 2015 to 2025). An increased concentration of ammonia in the blood. "HY occurring after physical exercise directs toward SCL16A1 mutation; post prandial HY, especially if associated with epilepsy or hyperammonemia, can suggest GLUD1 mutation." (PMID 32928245, 2020). "Therefore, GLUD1 and HADH patients present similarly with protein sensitivity, although GLUD1 mutations also cause hyperammonemia." (PMID 28855921, 2017). "Hepatic protein expression of the UCEs, OTC, CPS1, and GLUD1 were significantly down-regulated in hyperammonemia, which was restored upon treatment with OP and TAK-242." (PMID 40053595, 2025). "Most cases of HHS are due to heterozygous missense mutations in the GLUD1 gene, which encodes GDH, resulting in hypoglycemia and hyperammonemia, usually with onset in infancy and childhood." (PMID 40573270, 2025). "Hep-Glud1−/− mice exhibited impaired alanine induced gluconeogenesis and constitutive hyperammonemia." (PMID 38879007, 2024). "Surprisingly, consumption of the 45% protein diet by Hep-Glud1−/− mice fully reversed the hyperammonemia observed in KO mice fed the 20% protein diet." (PMID 38879007, 2024). "On a standard 20% protein diet, Hep-Glud1−/− mice displayed hyperammonemia accompanied by a rise in plasma bicarbonate levels and CO2 partial pressure." (PMID 38879007, 2024). "Ammonia was rarely determined, and it should be remembered that hyperammonemia directs the clinical and molecular diagnosis and the clinical conduct regarding the GLUD1 gene." (PMID 25972930, 2015). "GLUD1–CHH patients present with high levels (two to three times the normal) of plasma ammonia; however, they do not develop the symptoms associated with hyperammonemia." (PMID 27065949, 2016). "It has been reported that some HADH–CHH patients are also leucine sensitive, however, unlike GLUD1–CHH patients, they do not present with hyperammonemia." (PMID 27065949, 2016).
breast cancer (12 papers, 2007 to 2025). A primary or metastatic malignant neoplasm involving the breast. "For instance, GLUD1 expression is elevated in lung and breast cancers but decreases in clear cell renal cell carcinoma." (PMID 38587834, 2024). "GLUD1 inhibitors have been shown to attenuate the proliferation of breast cancer cells in mouse models." (PMID 37731509, 2023). "For example, breast cancer cells were shown to assimilate ammonium through GLUD1 activity by increasing the conversion of αKG to glutamate." (PMID 35629973, 2022). "GLUD1 is included in the pathway, and its low expression is positively correlated with the activity of nitrogen metabolism and poor prognosis of breast cancer." (PMID 36077657, 2022). "In breast cancer, GLUD1 expression is significantly higher in ER+/HER2− tumors than in other subtypes." (PMID 35847357, 2022). "In lung and breast cancers glutamate dehydrogenase 1 (GLUD1), instead of GOT1/2, produces α-KG and subsequently fumarate, which activates glutathione peroxidase 1, regulating the cellular antioxidant response at an additional level." (PMID 31288436, 2019). "For example, our analysis showed that glutaminase is frequently reported in PubMed abstract in reference to breast cancer, whereas the classic mitochondrial glutamate oxidation enzyme, GLUD1, has only been once reported in this context." (PMID 31231467, 2019). "However, in highly proliferative breast tumors, GLUD1 was also reported to be expressed in low level, indicating that the controversial role of GLUD1 in breast cancer." (PMID 36203437, 2022). "GLUD1 promoted breast cancer growth through accelerating metabolic recycling of ammonia." (PMID 36203437, 2022).
glioblastoma (12 papers, 2016 to 2024). The most malignant astrocytic tumor (WHO grade IV). "It interacts with MEK and ELK1 (ETS like-1 protein) to activate GDH1 (glutamate dehydrogenase 1) in response to epidermal growth factor receptor signalling in glioblastoma." (PMID 38699532, 2024). "Low GLUD1 levels in IDH1-WT glioblastoma, thus, correlate well with increased glutamate tissue levels." (PMID 34941573, 2022). "In glioblastoma, particularly in the mesenchymal subtype, the downregulation of both genes and proteins (GLUD1 and GPT2) increases the source of glutamate for GSH synthesis and enhances tumor cell fitness due to increased antioxidative capacity." (PMID 33910646, 2021). "In glioblastoma, glutaminolysis was found to occur via the upregulation of glutamate dehydrogenase 1 (GDH1)." (PMID 33854965, 2021). "The results are consistent with those of a previous report in which GLUD1 was shown to have an important role under the condition of glucose deprivation in glioblastoma cells." (PMID 27924922, 2016). "Furthermore, IL-11Rα expression in glioblastoma patient samples correlated with enhanced gene expression of the glutaminolysis pathway genes GLUD1, GSS and c-Myc." (PMID 36834778, 2023). "In our present study, we connect these independent findings identifying that IL-11Rα expression correlates with both increased c-MYC and GLUD1 expression in glioblastoma patient tumor tissue and enhanced glutaminolysis leading to significantly greater survival in glucose-starved conditions." (PMID 36834778, 2023). "Indeed, glioblastoma patient tumor tissue with low IL-11Rα gene expression also displayed low levels of GLUD1 and GSS, while patient tumor tissue containing high IL-11Rα gene expression also contained significantly higher levels of GLUD1 and GSS gene expression." (PMID 36834778, 2023). "Genes coding for GLUD1 and GPT2 expression levels varied according to the grade of malignancy, being downregulated in glioblastoma, and upregulated in lower grades of astrocytoma (AGII–AGIII)." (PMID 33910646, 2021). "Furthermore, high IL-11Rα expression also correlated with increased expression of GLUD1 and GSS, two key enzymes involved in glutaminolysis in both our glioblastoma cell lines and patient tumor tissue." (PMID 36834778, 2023). "Four abnormally expressed metabolic enzymes, glutaminase (GLS), glutamate dehydrogenase 1 (GDH1), hexokinase 2 (HK2) and glucose-6-phosphate dehydrogenase (G6PD), which directly affect metabolites in certain pathways, were found to be downregulated by Chr-A in glioblastoma cells." (PMID 39330272, 2024).